KRAS (KRas proto-oncogene, GTPase)
Diseases named in the same sentence as KRAS in open-access papers (continued):
Sharing a sentence is not in itself a finding about the gene and the disease.
lung cancer (continued). "At first sight, these later studies suggested that the relatively limited effect of vistusertib in STK11 deficient/KRAS mutant lung cancer might have been predicted." (PMID 40069402, 2025). "Additionally, the senescent-associated secretory phenotype contributed to TAMs promoting KRAS-mutated lung cancer." (PMID 40611261, 2025). "Given the increasing reliance on genetic and biomarker testing (EGFR, ALK, ROS1, PD-L1, and KRAS mutations) for targeted treatments, the ability to perform molecular analysis on minimally invasive samples represents a significant advancement in lung cancer care." (PMID 40805957, 2025). "Co-occurring mutations in the tumor suppressor LKB1 are frequent in KRAS-mutant lung cancers." (PMID 40316540, 2025). "Missense mutations in the twelfth codon of KRAS are key drivers of lung cancer." (PMID 40890128, 2025). "Furthermore, this review specifically discusses the impact of epidermal growth factor receptor (EGFR) and KRAS mutations on lung cancer progression and the consequent immune escape mechanisms they engender." (PMID 40847555, 2025). "Additionally, our study suggests LKB1 loss as a genotypic marker for sensitivity to KRASG12C-selective inhibitors + MCL-1 inhibitors in LKB1-deficient KRAS-mutant lung cancer cells." (PMID 40316540, 2025). "Notably, KRAS mutations are frequently observed in various cancers, including pancreatic, colorectal, and lung cancers, where they are associated with high mutation frequencies." (PMID 40344393, 2025). "Patients with lung cancer harboring a KRAS oncogenic driver mutation have a very poor prognosis." (PMID 40935852, 2025). "Notably, two key target variants, EGFR c.2369C > T and KRAS c.35G > T, are of clinical relevance for lung cancer." (PMID 40465784, 2025). "This review highlights the evolving landscape of therapeutic strategies for actionable mutations in lung cancer, with particular attention given to the latest developments in KRAS-targeted treatments including non-G12C mutations, pan-RAS inhibitors, and agents targeting RAS-GTP." (PMID 41373672, 2025). "Some radioresistant and chemoresistant mechanisms in lung cancer are related to KRAS mutations." (PMID 40361506, 2025). "Data on CPS in the presence of KRAS mutation were available only for lung cancer cases (n = 4)." (PMID 41515496, 2025). "Assays typically survey driver mutations relevant to lung cancer biology and therapy resistance – such as KRAS, PIK3CA and EGFR – and clonal‐haematopoiesis (CH) genes like DNMT3A and TET2, which are monitored to distinguish tumour DNA from age‐related background variants." (PMID 40847555, 2025). "Patients with KL expression subtype tumors may derive better OS and PFS from abemaciclib versus erlotinib in KRAS-mutated non–small cell lung cancer." (PMID 40231258, 2025). "Considering the strong synergistic effects of WEE1 kinase inhibitors with other downstream target inhibitors in KRAS-mutated lung cancer, we hypothesize that WEE1 inhibitors can also exert synergistic effects with KRAS G12C targeted inhibitors." (PMID 40885709, 2025). "Targeted therapies such as Sotorasib—a tyrosine kinase inhibitor—selectively binding KRAS G12C mutated proteins have been reported to be effective in KRAS G12C mutated lung cancer patients with good tumor responses and better progression-free survival of patients." (PMID 40361506, 2025). "Of the three RAF paralogs (A-, B- and CRAF), CRAF has been implicated as the most important for initiating KRAS-driven lung carcinoma, while it is dispensable for KRAS-driven oncogenesis of pancreatic cancer, indicating that the dependency of tumor growth on RAF family members is context-specific." (PMID 41023593, 2025). "The KRASG12R mutation, which accounts for approximately 15% of the KRAS mutations in pancreatic cancer but less than 1% of the KRAS mutations in lung cancer, was reported to be associated with different downstream signaling pathways relative to other KRAS mutations." (PMID 38310130, 2024).
lung cancer (continued). "This trend may be attributable to the different mutation rates of genes such as EGFR, ALK, and KRAS in younger versus older lung cancer patients." (PMID 38568892, 2024). "Consequently, a ‘one drug fits all’ approach to targeting KRAS mutant lung cancer is challenging, and treatment should be tailored to the subtype of KRAS mutation." (PMID 39533328, 2024). "However, lung cancer patients with HER2 mutations developed more brain metastases during treatment than patients with KRAS (28% vs. 8%, hazard ratio [HR] 5.2, P < 0.001) and EGFR mutations (28% vs 16%, HR 1.7, P = 0.06)." (PMID 39012378, 2024). "MPLC is dominated by KRAS mutations in European and American populations, likely reflecting the overall known geographic differences in genomic profiles of lung cancer." (PMID 38313018, 2024). "Furthermore, the KRAS gene ranked 10th in mRNA data, and it is a gene closely associated with lung cancer, with KRAS mutations present in 35% of LUAD cancer." (PMID 39470306, 2024). "Similarly, we investigated cell lines with mutations in KRAS, one of the most commonly mutated genes in lung cancer." (PMID 38483480, 2024). "In other words, the investigation of KRAS mutation in lung cancer, prognosis evaluation for patients with BRAF or RAS mutations, and elucidation of EGFR’s role in NSCLC and lung adenocarcinoma represent pivotal research directions within this field that have made significant advancements." (PMID 38706597, 2024). "This has profound implications for identifying and treating KRAS-driven tumors, and different combinations of downstream signaling pathway inhibitors may be required when treating KRAS mutation lung cancer with different amino acid substitutions." (PMID 38734764, 2024). "For instance, both mutation and high amplification could be detected in EGFR, MET, and ERBB2 in lung cancer, as well as mutations in KRAS, BRAF, STK11, KEAP1 and many others." (PMID 39289779, 2024). "In addition, we proposed several FDA-approved cancer-targeted drugs for various cancer types through PRISM drug screens, such as cabazitaxel for VHL-mutated kidney cancer and alectinib for lung cancer with NRAS or KRAS mutations." (PMID 37863651, 2024). "Oncology experienced a similar revolution about a decade ago, where instead of treating cancer in a single organ (e.g., lung cancer) as a single disease, treatment, and prognosis are now based on the genomic profile of the cancer cells (e.g., cancers with KRAS mutations and low PD-L1 expression)." (PMID 39609319, 2024). "Hence, alteration to lipid metabolism warrants further study as a potential biomarker and target for therapy in patients with KRAS-mutated lung cancer." (PMID 39113608, 2024). "In KRAS-mutated lung cancer, CDKN2A mutation was associated with worse survival on imunotherapy." (PMID 38310130, 2024). "Moreover, it has been reported that genes most frequently co-mutated with KRAS vary with the KRAS mutation alleles in patients with lung cancer, and these different patterns of co-mutation with KRAS differentially affect clinical outcomes." (PMID 38310130, 2024). "Furthermore, it has been reported that chemotherapy treatment of lung cancer with KRAS mutations causes hyperactivation of mTORC1 signaling." (PMID 39385301, 2024). "Furthermore, statins can overcome EGFR-TKI resistance in patients with lung cancer harboring KRAS mutation, and they provided an increased response rate in lung cancer patients previously treated with nivolumab." (PMID 38478558, 2024).
lung cancer (continued). "In the last few years, an increasing number of small-molecule anti-cancer drugs, the so-called GTPase inhibitors as well as others, has been tested in clinical trials, generating encouraging results with improved efficacy of lung cancer treatment for KRAS-mutated NSCLC." (PMID 38846975, 2024). "With regard to lung cancer, KRAS driver-mutations are found in both KP and LLC tumors." (PMID 38254785, 2024). "Therefore, targeting SREBP-regulated fatty acid synthesis is a unique therapeutic target for KRAS-mutated lung cancer." (PMID 39744129, 2024). "These new hits have the potential to inhibit KRASG12C and may help to prevent KRAS-associated lung cancer." (PMID 38528576, 2024). "In particular, about 50% of KRAS-mutated lung cancer exhibit also deletions in LKB1." (PMID 39763604, 2024). "Importantly, the authors found that STING silencing was associated with LKB1 loss also in KRAS WT lung cancers, and was especially robust when combined with elevated DNMT1 levels, suggesting that this mechanism is not purely limited to the KL cellular state." (PMID 38791897, 2024). "In addition, p38 generally functions as a tumor suppressor protein; however, in vitro experiments have shown that it contributes to cell proliferation and malignant transformation in transgenic lung cancer cell lines harboring the KRAS G12V mutation." (PMID 38433247, 2024). "For example, tamoxifen, an FDA-approved inhibitor of the protein kinase C genes PRKCB and PRKCE, currently used for breast cancer treatment, could potentially be used to target EGFR or KRAS-mutated lung cancers and NRAS-mutated skin cancer." (PMID 37863651, 2024). "Notably, the founding members NRAS, HRAS, and KRAS are known proto-oncogenes, with KRAS frequently mutated in pancreatic and lung cancers." (PMID 39095874, 2024). "KRAS mutations, the most common type of driver mutation in lung cancer, often found in individuals with a history of smoking, have recently been targeted by sotorasib, a new agent directed at KRAS G12C mutations, showing a response rate of 32% in clinical trials." (PMID 39001401, 2024). "Here, we used the urethane-induced tumors that closely resemble human lung cancers in terms of histopathology and progression and often exhibit genetic mutations and molecular alterations similar to those found in human lung cancer, such as mutations in the KRAS gene." (PMID 39272828, 2024). "Together with a case report of an individual with STK11/KRAS co-mutated advanced lung cancer with near complete response to pembrolizumab and platinum-doublet therapy, these data suggest that STK11 mutation should not be used as a strict exclusion criterion for immune checkpoint blockade in NSCLC." (PMID 39172022, 2024). "As is well known, pro‐oncogene KRAS mutation frequently occurs in lung carcinoma." (PMID 39323079, 2024). "Therefore, in the present study, we evaluated the effectiveness of a pre-selected small-molecule PERK inhibitor on human lung carcinoma epithelial cells (A549)—a representative NSCLC cell line with mutations in the KRAS gene." (PMID 38672243, 2024). "KRAS mutations have been linked to better immunotherapy responses in lung cancer." (PMID 37208639, 2023). "In lung cancer, a study found that KRAS mutations could promote the cell growth of lung cancer cells with SLC3A2-NRG1 (S-N) fusion." (PMID 36675641, 2023). "STK11/LKB1 inactivation is common in KRAS-mutated lung cancer." (PMID 37670322, 2023).
lung cancer (continued). "A study of immune checkpoint inhibitors (ICIs) in lung cancer patients with brain metastasis showed that KRAS mutations may drive a better efficacy of immunotherapy." (PMID 36675641, 2023). "Several genes’ mutations were found to be a good prognostic marker for human cancer; examples include mutated KRAS that was correlated with poor prognosis of pancreatic and lung cancer and mutated NRAS that was correlated with poor prognosis of metastatic melanoma." (PMID 37033447, 2023). "If until recently the KRAS mutation was considered un-targetable, the recent introduction of specific inhibitors of the KRAS G12C mutation in patients with advanced lung cancer has been followed with great enthusiasm, considering that about half of patients with mCRC has a KRAS mutation." (PMID 37909027, 2023). "Similarly, combined ADAM17 and MEK inhibition led to greater tumor growth inhibition in KRAS-mutated lung cancer, compared to MEK inhibition alone." (PMID 37190303, 2023). "KRAS mutations render lung cancer cells insensitive to phagocytosis by macrophages." (PMID 36413402, 2023). "KRAS-mutated NSCLC is the most common type of oncogenic-driven lung cancer in Western populations." (PMID 37373999, 2023). "To further support the idea of miR-708 as a precision medicine for NRAS mutation-driven cancers, we overexpressed miR-708 in breast cancer cells and lung cancer cells carrying KRAS mutation, MDA-MB-231 and A549, as well as normal lung epithelial cells, BEAS-2B." (PMID 37083947, 2023). "EGFR and KRAS are two other frequently mutated genes in lung cancer." (PMID 37696458, 2023). "In addition, most KRAS inhibitors have been developed to target the KRAS-G12C mutation, which constitutes only a portion of the KRAS mutations and is commonly found in lung cancer." (PMID 37662925, 2023). "Our data suggest that in KRAS-driven lung cancers, a PRC2-deficient state, either occurring naturally or through EZH2 inhibition, may be vulnerable to BET inhibition." (PMID 36670102, 2023). "KRAS G12C mutations occur most often in lung cancer, accounting for nearly 50% of KRAS-mutant LUAD." (PMID 37581538, 2023). "There are characteristic co-occurring mutations in KRAS mutant lung cancer such as STK11 and KEAP1." (PMID 38239281, 2023). "Our results reveal that TE RNA dysregulation in KRAS-driven lung cancer cells is mutation-dependent, while also highlighting a subset of young, Alu-derived TE RNAs that are coordinately activated with innate immunity genes upon KRAS(G12C) inhibition." (PMID 36909578, 2023). "Interestingly, although all samples in our cohort were lung cancer patients with metastases confined to bone, only 2 patients carried the KRAS G12C mutation but 3 patients harbored KRAS G12V mutation." (PMID 36755257, 2023). "KRAS‐positive lung cancers have been identified with KRAS mutations by tissue‐based analysis." (PMID 37751775, 2023). "KRAS is the main oncogenic driver in lung cancer that can be activated by gene mutation or amplification, but whether long non-coding RNAs (lncRNAs) regulate its activation remains unknown." (PMID 37041291, 2023). "These mutations, such as T790M or KRAS, are common in lung cancer." (PMID 37863665, 2023). "Their analysis showed that the mTOR inhibitor MLN0128 could suppress tumor growth and glycolysis in genetically engineered mouse models (GEMMs) of lung cancer with KRAS and LKB1 co-mutations, as shown by reduced 18F-FDG consumption." (PMID 37190124, 2023). "KRAS mutation can regulate β‐oxidation of fatty acids in non‐small cell lung cancer (NSCLC) and de novo synthesis processes to participate in tumor metabolic reprogramming and regulate fatty acid metabolic enzymes to regulate fatty acid production in lung cancer cells." (PMID 36994237, 2023). "The suppression of RHOA or FAK induces cell death selectively in KRAS-mutated lung cancer cells." (PMID 37569406, 2023).
lung cancer (continued). "Our findings provide the first evidence, to our knowledge, that KRAS mutations could suppress the innate antitumor immune response by regulating CD47 expression in lung cancer cells." (PMID 36413402, 2023). "KRAS mutations are significantly associated with poor outcomes in patients with lung cancer." (PMID 37662925, 2023). "STK11 and KEAP1 have been associated with a poorer prognosis in KRAS mutant lung cancer." (PMID 38067288, 2023). "Next, we tested whether ATR-PrimPol-mediated RST is maintained in lung cancer cells with oncogenic KRAS mutation." (PMID 37591859, 2023). "A new study in pancreatic ductal adenocarcinoma (PDAC), where almost 80% of cases are KRAS mutant, demonstrated that activating mutation in KRAS alone is sufficient to elevate levels of CD73 suggesting that CD73 induction with oncogenes extends beyond lung cancer." (PMID 37033953, 2023). "A potential strategy to find drug combinations targeting a larger fraction of KRAS-mutated lung cancers may capitalize on the common, distal gene expression output elicited by oncogenic KRAS." (PMID 37816716, 2023). "For example, a lung cancer study performed with Latin Americans showed that Native American ancestry was strongly correlated with mutations in the EGFR and KRAS genes, underscoring the importance of providing genetic testing for Latin American patients with lung cancer with admixed ancestries." (PMID 37039257, 2023). "This suggests that a combination of pan-RAF and STAT3 inhibitors could be an effective treatment for lung cancer cells with KRAS mutations." (PMID 38111008, 2023). "In addition, there are co-mutated genes such as ATM serine/threonine kinase gene (ATM), MNNG HOS Transforming gene (MET), and erb-b2 receptor tyrosine kinase 2 gene (ERBB2), which account for more than 10% of patients with KRAS mutated lung cancer." (PMID 36675641, 2023). "Acquired resistance to sotorasib treatment of lung cancer patients had various pathomechanisms At the first place it was found the disappearance of G12C mutation from cancer cells or the amplification of the wild type KRAS gene." (PMID 38239281, 2023). "For cancers with KRAS mutations, it is established that mtDNA release into the cytoplasm can activate STING, and suppression of STING has been linked to immune evasion in lung-cancer cells with KRAS mutations (in vitro and in SCID mice with xenografted human lung adenocarcinoma A549 cells)." (PMID 38139802, 2023). "Indeed, the LUAD cell line A549 harbors KRASG12S point mutation and is widely used as a representative lung cancer cell model with KRAS mutation." (PMID 37704611, 2023). "Recently, the KRAS G12C inhibitor sotorasib was approved as the world's first drug targeting KRAS, showing efficacy against unresectable advanced or recurrent non‐small cell lung cancer with KRAS G12C mutation‐positive disease that progressed after cancer chemotherapy." (PMID 37079001, 2023). "Importantly, SETD2 loss sensitized KRAS-mutant lung cancer to inhibition of histone chaperones, the FACT complex, or transcriptional elongation both in vitro and in vivo." (PMID 36810256, 2023). "The key function of K-Ras in this interaction is also supported by the enhanced sensitivity of KRAS-mutant lung cancer cells to MEK inhibition after ATM loss and radiosensitization of KRAS-mutated pancreatic cancer cells after MEK targeting through inhibition of HR- and NHEJ-dependent DSB repair." (PMID 36313934, 2023). "Mutation of the KRAS oncogene is a pivotal pathogenic event in lung cancer." (PMID 37511536, 2023). "STK11/LKB1 mutations were linked to resistance of PD-1 blockade in KRAS-mutant lung cancer." (PMID 36874015, 2023).